AFP (alpha fetoprotein)
Diseases named in the same sentence as AFP in open-access papers (continued):
Sharing a sentence is not in itself a finding about the gene and the disease.
tumor (continued). "We also found a higher male/female ratio, greater size of largest tumor and higher AFP level in the HBV-HCC group, and a greater number of tumors per patient and downstaging treatments in the HCV-HCC group." (PMID 23613886, 2013). "Univariate analyses showed that in the 65 patients who took sorafenib, PFS time correlated with age and OS time correlated with AFP level, tumor size, ascites, and tumor thrombus." (PMID 23552472, 2013). "Further, multivariate Cox regression analysis indicated that, as for TNM stage, GPC3 staining combined with serum AFP was an independent prognostic factor for postoperative outcome and tumor recurrence in HCC patients." (PMID 23537217, 2013). "On univariate analysis of our data, several clinical factors including AFP, tumor multiplicity, tumor size, vascular invasion and TNM stage showed prognostic significance for both OS and TTR." (PMID 23305119, 2013). "Multiple logistic regression analysis indicated that tumor diameter (≥ 5 cm) and preoperative serum AFP level (> 400 ng/mL) were closely correlated with HCC postoperative survival rate (P <0.05)." (PMID 23981851, 2013). "The correlation between serum GP73 and tumor size and HCC grading was analyzed and the complementary diagnostic value of serum GP73, AFP and GGT-II was evaluated." (PMID 24137480, 2013). "Our group reported that tumor size and AFP were strongly related to the presence of microvascular invasion (MVI) on the explanted liver." (PMID 24455285, 2013). "Blood test results, including the levels of the tumor markers, carcinoembryonic antigen, α-fetoprotein (AFP) and carbohydrate antigens 19-9 and 12-5, were within normal limits." (PMID 24273602, 2013). "In the univariate analysis, serum AFP>200 ng/dL, serum γ-GT >50 U/L, tumor size >5 cm, presence of microvascular invasion, and advanced TNM stage were risk factors for both OS and RFS." (PMID 23555776, 2013). "But the MUC2 mRNA was elevated in tumor tissues with AFP > = 30 (μg/l) than those with AFP < 30 (μg/l) in HCC patients (Mean -ΔCt ± SE, -3.73 ± 0.75 and −6.25 ± 0.94, respectively) (p = 0.040)." (PMID 23347460, 2013). "Multivariate analysis showed that serum AFP (≥400), TNM stage, loss of 8p12-p23.2 were independent factors associated with tumor-free survival (all P-values ≤ 0.045)." (PMID 24391771, 2013). "The OS was statistically significantly correlated with seven factors such as AST, serum AFP, tumor size, tumor differentiation, portal vein invasion, stage of tumor, and PTP4A3/PRL-3 expression." (PMID 23064776, 2013). "CA125 level in our model was high in both serum and ascites supernatants, while levels of other tumor markers, such as AFP, CA-199 and CEA, were normal." (PMID 23384043, 2013). "Multivariate analysis with step-wise variable selection showed that the risk factors for extra-subsegmental recurrence were age, platelet count, tumor size, and AFP." (PMID 23593129, 2013). "It has also been reported that cases with high AFP levels have a poor prognosis due to a correlation between tumor size and AFP." (PMID 23452898, 2013). "Previous articles have already reported on the role of Child-Pugh classification, tumor size, AFP prior TACE and the proportion of tumor necrosis in the prediction of treatment response and survival." (PMID 24198841, 2013). "Nevertheless, no consistent correlation has been established between serum AFP level and tumor stage, degree of tumor differentiation, or extrahepatic metastasis." (PMID 23981851, 2013). "The final model for predicting intra-subsegmental recurrence with stepwise variable selection included tumor size, AFP, platelet count and anti-HCV antibody positivity." (PMID 23593129, 2013). "Our results indicated a potential role for IL-6, and IL-10 as a tumor marker for HCC with respect to AFP and this was in agreement with the previous studies." (PMID 27335826, 2013).
tumor (continued). "With a cohort of 86 randomly selected HCC patients, we investigated the potential downregulation of the LEPREL1 with numerous clinical parameters, including age, gender, tumor size, Edmondson grade, vascular invasion, and AFP." (PMID 24319452, 2013). "The tumor markers performed at presentation demonstrated normal values for both hCG and AFP whereas the CA-125 level was moderately elevated at 368U/mL (normal range 0 to 35)." (PMID 23856407, 2013). "This can be due to certain ‘leakiness’ of the AFP promoter or the hCMV enhancer element, as it has been observed for viral vectors with tissue or tumor specific promoters." (PMID 23734827, 2013). "In case 1 of this report, although the main tumor had ambiguous radiologic morphology and the tumor markers AFP and PIVKA were within normal ranges, our preoperative diagnosis was an HCC." (PMID 24313990, 2013). "Parameters, including tumor size, tumor number, vascular invasion, presence of satellite lesions and serum alpha-fetoprotein (AFP) level, have been reported to be useful predictors." (PMID 24260043, 2013). "Tumor markers were as follows: alpha fetoprotein (AFP) 3.87, CA 199, and carcinoembryonic antigen (CEA) 2.29." (PMID 23497239, 2013). "In sharp contrast to the AFP driven plasmid, luciferase activity in lung was 20-fold lower, whereas the luciferase expression in tumor was unaffected." (PMID 23734827, 2013). "The tumor markers alpha-fetoprotein (AFP), carcinoembryonic antigen (CEA), and CA19-9 were all within normal ranges." (PMID 24368955, 2013). "Only one nodule with tumor size of 1.2 cm (serum AFP level of 84.6 μg/L) showed a regular enhancement on the arterial phase." (PMID 23800233, 2013). "In sharp contrast, lung activity was strongly reduced with pEPito-hCMV/AFP-ofLuc polyplexes, and in some animals a weak signal was observed in the tumor area." (PMID 23734827, 2013). "The tumor size standardization demonstrated a drastic 6.7 fold elevation of AFP in the ≤44 group with 29,124±3,382 ng/ml/tumor-cm, compared to the 4,331±311 ng/ml/tumor-cm of the >44 group (P<0.0001)." (PMID 23840771, 2013). "In young woman (<35 years), additional tumor markers like inhibin, AFP or B-hCG, should be measured if clinically indicated." (PMID 23468275, 2013). "Tumor markers, such as positive AFP or beta-hCG in the blood and cerebrospinal fluid concentrations of patients would also be helpful in clinching the preoperative diagnosis of medullary germinoma." (PMID 24127860, 2013). "AFP is produced by malignant retroperitoneal teratomas and functions as a specific tumor marker for laboratory diagnosis." (PMID 24137347, 2013). "Significant differences were observed in the median number of tumors, median diameter of the largest tumor, and median preoperative AFP level between the PLT and SLT recipients." (PMID 22574187, 2012). "Tumor diameter correlated with necrosis, AFP level, and multiplicity (P = 0.054, P < 0.001, and P = 0.021 respectively)." (PMID 23162604, 2012). "Regression in tumor size and reduction in mean AFP levels were reported in 45.5% and 50% of the cases respectively." (PMID 23166534, 2012). "The tumour cells have an epithelial histology and express HCC-associated proteins such as Alpha-fetoprotein (AFP), Glypican 3, E-cadherin, CD10, CD326, HepPar1 and Vimentin." (PMID 22666492, 2012). "Of the other variables, serum AFP level (P<0.0001), tumor multiplicity (P = 0.021) and vascular invasion (P = 0.008) were evaluated as well independent prognostic factors for patients' overall survival." (PMID 22393452, 2012). "Serum detection showed tumor markers such as alpha fetoprotein (AFP), carcinoembryonic antigen (CEA), carbohydrate antigen 50 (CA-50), carbohydrate antigen 19–9 (CA-19-9) were all in the normal range." (PMID 22735126, 2012). "In this study, we examined the diagnostic value of the CA 19-9, CA 125, CEA, CA 15-3, AFP and PSA for the diagnosis of tumour aetiology in patients with PE." (PMID 22555638, 2012).
tumor (continued). "Several arguments point out that HCC tumor cells can infiltrate the blood system as shown by the presence of alpha-fetoprotein mRNA." (PMID 22690340, 2012). "The Child-Pugh classification is used to evaluate the status of liver function, and serum AFP is the most useful tumor marker to reflect tumor burden in HCC." (PMID 22292912, 2012). "It has been confirmed in numerous investigations that AFP serum concentration increase in parallel with HCC tumor size." (PMID 23162601, 2012). "Abnormal serum tumor markers were: alphafetoprotein (AFP) 6679 IU/ml, human chorionic gonadotropin 8 mIU/ml, testosterone 1.75 ng/ml and inhibin B 346 pg/ml." (PMID 23217189, 2012). "In the animal experiment, AFP-DC and IL-2-DC vaccines inhibited the tumor growth significantly compared with the DC vaccine; however, the tumor inhibition by AFP/IL-2-DC vaccine was the most potent." (PMID 23170121, 2012). "Alpha-fetoprotein (α-fetoprotein, AFP) is a large serum glycoprotein, used as a tumor marker for HCC." (PMID 23166534, 2012). "The traditional factors for tumor recurrence such as AFP, however, still showed significant difference in RFS even among small number of patients enrolled in the current study." (PMID 23132957, 2012). "Significant correlations were found between PLK4 expression and three parameters including clinical stage (P = 0.034), serum AFP positive (P = 0.019) and tumor size (P = 0.032)." (PMID 22829937, 2012). "Subcutaneous xenotransplantation of HC-AFW1 cells into NOD/SCID mice resulted in fast growing dedifferentiated tumours with high levels of serum AFP." (PMID 22666492, 2012). "In very recent years, AFP has been proposed as a predictor of patient survival and tumor recurrence after surgery, locoregional therapies, and systemic chemotherapy." (PMID 22792474, 2012). "Downregulation was significantly associated with advanced HCC stages, indicated by a higher number of T3 tumors (p = 0.025) with a larger tumor diameter (p = 0.035), a worse differentiation (p = 0.001) and higher AFP-levels (p = 0.019)." (PMID 22439694, 2012). "In Korea, a scoring system incorporating tumor size, number, and AFP has been proposed for the selection of transplant candidates." (PMID 22690340, 2012). "Results indicated that SIRT3, as well as tumor size, serum AFP level, tumor multiplicity, clinical stage, vascular invasion, tumor differentiation, and relapse, was responsible for outcome of HCC patient who underwent surgical resection." (PMID 23272146, 2012). "Alphafetoprotein (AFP) remains the most widely used tumour marker of HCC detection in spite of its known shortcomings." (PMID 22856336, 2012). "Tumor markers levels were high, with a total inhibin of 1,069U/L and an alpha-fetoprotein of 987 μg/L." (PMID 22734844, 2012). "The failure of serum AFP levels to return to normal after surgery is an indication of either incomplete tumor resection or metastases." (PMID 22312308, 2012). "rHsp70 was as effective as rHsp70C′-PSA or rHsp70C′-AFP in inducing a tumor-specific cytotoxic T lymphocyte response or tumor growth delay." (PMID 23112956, 2012). "After tumor resection and irradiation, serum AFP concentration was to 2.4 ng/ml and HCG level was <1.0 mIU/ml." (PMID 22286191, 2012). "Decreased PLK4 expression in HCC is significantly related to tumor size, serum AFP, and clinical stage." (PMID 22829937, 2012). "This new role derives from the strong correlation detected between AFP values, tumor dimensions, and microvascular invasion, all well-known predictors of HCC recurrence." (PMID 22792474, 2012). "Tumor differentiation and vascular invasion and serum AFP are the most commonly agreed survival indices for affecting the prognosis of HCC patients." (PMID 22829937, 2012). "Despite the existing uncertainty concerning its biologic role, an increase in the serum concentration of AFP is primarily used as a tumor marker for HCC evaluation." (PMID 23162601, 2012).
tumor (continued). "An immunohistochemical study of the tumor cells showed diffuse positive staining for alpha-fetoprotein and focal areas of positive staining for inhibin." (PMID 22734844, 2012). "Independent, preoperatively evaluable risk factors for early death were identified by multivariate analysis as AFP > 1,000 ng/ml, tumor number ≥ 4, and tumor size ≥ 5 cm." (PMID 22697061, 2012). "Despite its limitations, serum AFP still remains the most widely used tumor marker in clinical practice." (PMID 22655201, 2012). "HCC patients with low PLK4 expression had a higher tendency to be with advanced stage, high level of serum AFP and large-size tumor." (PMID 22829937, 2012). "rHsp70 was as effective as rHsp70C′-PSA or rHsp70C′-AFP in inducing a tumor-specific CTL response or tumor growth delay." (PMID 23112956, 2012). "Recent studies have shown that several parameters like tumor size, portal invasion, alpha fetoprotein (AFP), Child-Pugh score, bilirubin, ascites, performance status and therapy response were independent predictors of survival after TACE." (PMID 22970277, 2012). "About the tumor marker, only a few of patients have slightly elevated tumor marker levels, such as serum alpha-fetoprotein (AFP, 7/68), carcinoembryonic antigen (CEA, 1/41), carbohydrate antigen 19-9 (CA19-9, 3/34)." (PMID 22221822, 2012). "Further analysis showed that overexpression of cytoplasmic ZEB2 in HCCs was inversely correlated with AFP level, tumor size and differentiation (P<0.05)." (PMID 22393452, 2012). "As the AFpg promoter has not been evaluated in vivo, we examined the cytotoxic effect of specific expression of DN-PP2Acα, driven by the AFpg promoter, in AFP-positive cells using a tumor xenograft model." (PMID 23173703, 2012). "Serum tumor markers, such as alpha-fetoprotein (AFP) and des-gammacarboxy prothrombin (DCP) are commonly used for the surveillance, but their roles have been intensely debated despite the existence of sensitive radiologic tests." (PMID 23162601, 2012). "Multivariate analysis demonstrated that age, Child–Pugh class, tumour size, tumour number and serum alpha-fetoprotein level were significant prognostic factors for survival." (PMID 22712520, 2012). "Significant correlations were found between SIRT3 expression and variables including differentiation (P = 0.013), clinical stage (P = 0.005), serum AFP level (P<0.01), tumor multiplicity (P = 0.026) and relapse (P = 0.028)." (PMID 23272146, 2012). "The levels of tumor markers, including α-fetoprotein (AFP), protein induced by vitamin K absence-II (PIVKA-II), carcinoembryonic antigen (CEA), carbohydrate antigen (CA) 19–9, and cancer antigen 125 (CA125), were within normal limits." (PMID 22540346, 2012). "Serum tumor markers, such as alpha-fetoprotein (AFP) and des-gammacarboxy prothrombin (DCP), are commonly used for the surveillance, but their roles are being intensely debated despite existence of sensitive radiologic tests." (PMID 23162601, 2012). "Ascites, bilirubin, alkaline phosphatase, AFP, number of tumor nodes and the BCLC tumor extension remained independent prognostic factors in multivariate analysis." (PMID 23071507, 2012). "This is plausible, if the functional activation of such therapeutics is dependent on the presence of a tumor-specific protein (e.g. AFP in some cases of HCC)." (PMID 22964488, 2012). "In particular the adverse effect of portal vein thrombosis, extra-hepatic spread, tumour multifocality and elevated AFP on patients OS has emerged from previously published studies." (PMID 22433965, 2012). "Serum tumor markers showed slight elevation of alpha-fetoprotein (AFP) at 15 μg/L (normal < 9 μg/L), normal β-human chorionic gonadotropin (β-hCG) < 5 U/L (normal < 5 U/L), and lactate dehydrogenase (LDH) 116 U/L (normal 100–225 U/L)." (PMID 23050178, 2012). "In multivariate analysis, a model that contained age, antibody to hepatitis C virus (anti-HCV), Child–Pugh class, tumour size, tumour number and serum AFP level was selected." (PMID 22712520, 2012).
tumor (continued). "Univariate analysis revealed that microvascular invasion, tumor number >1, macrovascular invasion, ascites, AFP>25 ng/mL, albumin ≤ 4.0 g/dL, and furin expression T/N ratio <3.5 were significantly associated with a shorter DFS." (PMID 22808247, 2012). "After 9 to 12 months, mice of lines 45-2 and 50-4 displayed increased alpha fetoprotein (AFP) levels, and tumor formation was recognized." (PMID 23233866, 2012). "Age, sex, etiology, Child-Pugh class, tumor size, tumor numbers, serum AFP, serum YKL-40, vein invasion, and number of TACE sessions were enclosed in the univariate analysis." (PMID 22970277, 2012). "As the number of the tumors was high and too numerous to count, the tumor load in the liver was analyzed only by the serum parameters AFP and GLuc." (PMID 21853130, 2011). "In recent studies, some parameters, such as tumor size, portal invasion, alpha fetoprotein (AFP), Child-Pugh score, bilirubin, ascites, and performance status were found to have prognostic and predictive impact if determined prior to TACE." (PMID 21615953, 2011). "The GIP peptide epitopes recognized HLA-A-0201/AFP primed tumor cells in cytotoxicity assays and induced interferon (IFN-alpha) cytokine production and secretion assays." (PMID 24212829, 2011). "AST, ALT, bilirubin and AFP levels, which were identified to be significant prognosis predictors in univariate analysis, reflected either the degree of inflammation (AST, ALT and bilirubin) or the tumor burden (AFP)." (PMID 22022601, 2011). "The Alpha-fetoprotein (AFP) derived Growth Inhibitory Peptide (GIP) is a 34-amino acid segment of the full-length human AFP molecule that inhibits tumor growth and metastasis." (PMID 24212829, 2011). "Further correlation analysis revealed that high expression of p300 in HCCs was correlated with higher serum AFP levels, larger tumor size, tumor multiplicity, poorer differentiation and later clinical stage." (PMID 21205329, 2011). "High expression of p300 was correlated with higher AFP level, larger tumor size, multiplicity, poorer differentiation and later stage (P < 0.05)." (PMID 21205329, 2011). "It is expected that recurrent HCC to have the identical bioactivity as the primary tumor and to exude high levels of AFP, making AFP an apparently reliable choice." (PMID 22087135, 2011). "Others have demonstrated that variables, such as higher total tumour burden, higher preoperative alpha-fetoprotein, and presence of tumour necrosis, predict significantly worse outcomes." (PMID 21994867, 2011). "At the sixth month the normalization of the alpha-fetoprotein level at the lower limit of normality was confirmed and the MRI showed complete disappearance of the neoplasia." (PMID 21241463, 2011). "Their strong correlation with tumour grade and vascular invasion and their prognostic power suggest that blood AFP mRNA and VEGF are direct markers of biological tumour aggressiveness." (PMID 21912636, 2011). "The patient has been under regular follow-up with clinical examination and liver function test every two months, with surveillance for tumor markers (AFP, CA19-9, CEA) and abdominal CT scan being done at 4 months intervals (last follow-up June 2011)." (PMID 21812959, 2011). "The increase of AFP and GLuc-activity were exponential and matched to the number of tumor nodules observed on the surface of the liver." (PMID 21853130, 2011). "We performed multivariate analysis with stage, portal vein thrombosis, platelet count, and tumor markers according to cut-off values of tumor markers for AFP (≥ 400 ng/mL) and PIVKA-II (≥ 300 mAU/mL)." (PMID 21985636, 2011). "As with other series, tumour size, histological grade, vascular permeation, preoperative serum alpha-fetoprotein, and preoperative MELD score correlated with survival and disease recurrence." (PMID 21994867, 2011). "The human α-fetoprotein (AFP) messenger RNA (mRNA) is generally accepted as a tumor-specific marker." (PMID 22087143, 2011).